KL (klotho)
Diseases named in the same sentence as KL in open-access papers (continued):
Sharing a sentence is not in itself a finding about the gene and the disease.
osteoporosis (continued). "Transgenic mice lacking klotho expression develop a phenotype characterized by accelerated aging, skin atrophy, lung emphysema, osteoporosis, delayed wound healing, and vascular calcification." (PMID 28912623, 2017). "When these two molecules, Klotho and NGF, were examined, it was shown that they were produced by many different organs and cell systems in the peripheral system and played a role in many diseases from neuroinflammation to cancer, such as osteoporosis and aging." (PMID 34763683, 2021). "Previous research reported that mice lacking the Klotho gene developed osteoporosis." (PMID 29665846, 2018). "The absence of KL gene expression in mice leads to the appearance of various phenotypes similar to human aging, such as arteriosclerosis, osteoporosis, emphysema, life-span shortening, skin and muscle atrophy, cognitive impairment, hearing loss, and movement disorders." (PMID 26379754, 2015). "In particular, we could not adjust for bone formation (osteoporosis, fracture, and bone density), which is decreased in diabetic patients, PTH, soluble Klotho, and vitamin D status." (PMID 29996526, 2018).
Cognitive impairment (51 papers, 2013 to 2026). Abnormal cognition is characterized by deficits in thinking, reasoning, or remembering. "Klotho deficiency was associated with cognitive impairment, reduced growth, diminished longevity and the development of age-related diseases in vivo." (PMID 38213484, 2024). "The mechanism underlying low serum Klotho levels increasing the risk of cognitive impairment is multifactorial." (PMID 37560310, 2023). "Higher level of serum Klotho were significantly associated with lower odds of cognitive impairment in patients with UACR > 30mg/g." (PMID 37560310, 2023). "Previous reports show that KL in the brain is required for maintaining normal cognitive function in mice, since global knockdown of KL in the mouse brain causes cognitive deficit." (PMID 36674721, 2023). "We observed that vitamin C, with its antioxidant and anti-inflammatory properties, is strongly linked to Klotho protein-related chronic conditions, such as cognitive impairment and cardiovascular disease." (PMID 38231677, 2023). "The importance of klotho in healthy central nervous system (CNS) function was identified through klotho-deficient mice, where there were significantly fewer Purkinje cells in the cerebellum, diminished axonal transport and cognitive impairment." (PMID 34194816, 2021). "Mice with klotho gene knockout displayed increased susceptibility to cognitive impairment relative to the WT littermates." (PMID 34306305, 2021). "The upregulation of Klotho levels in the brain and serum significantly ameliorated Aβ burden, neuronal and synaptic loss and cognitive deficits in aged APP/PS1 mice." (PMID 32964663, 2020). "Although increased klotho was correlated with cognitive deficits in schizophrenia patients, the causal relationship between klotho levels and cognitive impairments is still undetermined." (PMID 32612508, 2020). "It is possible that the pathogenic cell environment in patients positively affects klotho activity, counteracting the cognitive impairments of patients with schizophrenia." (PMID 32612508, 2020). "Klotho-deficient mouse models rapidly develop cognitive impairment and show some evidence of neurodegeneration." (PMID 32188018, 2020). "Cox regression was used to assess the association between serum klotho and cognitive impairment of dialysis patients with cerebrovascular disease or cerebral infarction." (PMID 30791885, 2019). "Klotho−/− mice exhibit multiple phenotypes resembling human premature aging, including extremely shortened life span, cognitive impairment, hippocampal neurodegeneration, hair loss, atrophy of skin and muscle, ectopic calcification, osteoporosis, etc.." (PMID 29195509, 2017). "In older women, serum klotho may be used as a biomarker for risk stratification of cognitive impairment." (PMID 38468203, 2024). "Because considerable evidence has confirmed the importance of Klotho in both depression and cognitive impairments, which often coexist, it is suggested that Klotho may be a molecular factor linking these disorders." (PMID 37894946, 2023). "Studies have found that normal brain aging in rhesus monkeys was associated with down-regulation of klotho expression, and loss of klotho could accelerate the development of cognitive deficits." (PMID 36819720, 2023). "We investigate whether blood klotho concentrations are linked with cognitive impairment in a nationally representative sample of people in the United States." (PMID 36819720, 2023). "Oxidative stress contributed to the ageing-associated cognitive impairment in klotho mutant mice and klotho knockout mice had a generalised increase in the global burden of oxidative stress in the CNS, indicating that klotho exerts antioxidant effects in the brain." (PMID 34194816, 2021). "Given that Klotho is an antagonist of endogenous Wnt/β-catenin activity, it is reasonable to speculate that if Klotho reduces Wnt activity, upregulation of Wnt could be associated with cognitive impairment." (PMID 32188018, 2020).
Cognitive impairment (continued). "Low serum Klotho levels have been reported to be associated with cognitive impairment; however, the mechanisms are unknown." (PMID 32188018, 2020). "However, this is a preliminary study, and further research using prospective study and animal experiments is needed to investigate the dynamic changes of klotho and the causal relationship between klotho and cognitive impairments in schizophrenia." (PMID 32612508, 2020). "Thus, we evaluated hippocampal-dependent spatial memory function in the same behavioral tasks where Klotho-deficient cognitive impairment was reported." (PMID 30911673, 2019). "Mice that were Klotho-deficient developed human-like premature aging phenotypes, including multiple organ failure, cognitive impairment, and a shortened life span, which could be rescued by Klotho overexpression." (PMID 29403373, 2017). "The main achievement of our study is the confirmation, in a clinical setting, that Klotho has potential neuroprotective effects, preserving or improving memory function not only in physiological aging but also in this post-operative setting characterized by an increased risk of cognitive impairment." (PMID 37693766, 2023). "Thus, our results indicated that exercise-linked irisin could prevent mortality and improve cognitive impairment after cerebral ischemia by regulating klotho expression." (PMID 34306305, 2021). "The present study reports a unique investigation of the effects of a well-reported cognition-enhancing gene, Klotho, at both its genetic and protein levels on cognitive impairment in schizophrenia." (PMID 40083947, 2025). "It was shown that the administration of AAV-Klotho to mice with a temporal lobe epilepsy model significantly attenuated hippocampal neuronal damage and cognitive impairment." (PMID 38203812, 2024). "These down-regulated transcripts and processes hence emerge as co-related to the cognitive impairments shared by Klotho KO and AD." (PMID 38862813, 2024). "In humans, KLOTHO gene heterozygosity (KL-VShet) leads to increased blood protein levels and protection from cognitive impairments." (PMID 39125677, 2024). "This review aimed to discuss the role of the Klotho protein in the pathogenesis of depression and cognitive impairments." (PMID 37894946, 2023). "The reduction in Klotho during depression through oxidative stress and inflammatory mechanisms paves the way for the development of cognitive impairment observed in AD." (PMID 37894946, 2023). "Conversely, supplementation with exogenous recombinant Klotho or Klotho overexpression show improved health conditions in mouse models of the lung–kidney axis, cognitive impairment, sepsis, and pulmonary hypertension." (PMID 38133288, 2023). "In a rat model of STZ-induced cognitive impairment, simvastatin increased hippocampal Klotho and improved cognitive function." (PMID 35903083, 2022). "Low Klotho levels correlate with neurodegenerative disease and cognitive impairment, as well as frailty." (PMID 35903083, 2022). "Overexpression of klotho enhances learning and memory ability and reverse synaptic and cognitive impairments in the animal experiment." (PMID 36032243, 2022). "In this cross-sectional study of 243 patients with AD and controls, CSF Klotho levels were significantly higher among controls and individuals with mild cognitive impairment due to AD compared with individuals with dementia due to AD." (PMID 36413367, 2022). "Recently, many studies have found that the upregulation of Klotho can improve pathological cognitive deficits in an AD mice model and have demonstrated that Klotho plays a role in the induction of autophagy, a major contributing factor for AD." (PMID 35327507, 2022). "Klotho mutant mice exhibit a shortened lifespan and impaired synaptic integrity and awareness, whereas klotho overexpression extends the lifespan and improves synaptic integrity and cognitive impairment in mice." (PMID 34306305, 2021).
Cognitive impairment (continued). "After pretreatment with exogenous irisin, improved cognitive impairment, upregulated protein expressions of klotho, MnSOD, and FOXO3a, and reduced ROS generation were observed in mice with MCAO." (PMID 34306305, 2021). "Klotho-induced autophagy activation and protein kinase B/mammalian target of rapamycin inhibition, suggesting that up-regulation of klotho in the brain promotes the autophagic clearance of amyloid-β and protects against cognitive deficits." (PMID 34194816, 2021). "We previously reported that Klotho lowered Aβ levels in the brain and protected against cognitive deficits in amyloid precursor protein/presenilin 1(APP/PS1) mice." (PMID 32964663, 2020). "We report that, similar to Klotho-deficient mice, FGF-23-deficient mice develop dose-dependent, hippocampal-dependent cognitive impairment." (PMID 30911673, 2019). "The present study aims to investigate the correlation between Klotho gene and mild cognitive impairment (MCI) in Uygur and Han populations in Xinjiang." (PMID 29088855, 2017). "Recent data also suggest that inactivation of the JAK2/STAT3 signaling axis and M1 mAChR downregulation play a critical role in cognitive impairment observed in KLOTHO mutant mice." (PMID 25961830, 2015). "Klotho, a pleiotropic protein, extends lifespan and enhances cognition, but whether it confers resilience to cognitive impairments in PD is unclear." (PMID 41916755, 2026). "Together, these findings indicate that klotho can counteract cognitive deficits related to PD, possibly by modulating α-syn levels, and these findings may be relevant to new therapeutic pathways for PD." (PMID 41916755, 2026). "A better understanding of the multiple mechanisms where klotho exerts its cognitive protective roles in older women may enable the identification of cognitive impairment and timely prevention and treatment." (PMID 38468203, 2024). "For example, AAV-Klotho was injected into the bilateral hippocampus of rats with a model of temporal lobe epilepsy, and after 9 weeks, it was found that AAV-Klotho induced Klotho overexpression in the hippocampus, effectively improved cognitive impairment, and had a neuroprotective effect." (PMID 38203812, 2024). "Moreover, Klotho is a promising molecular target for future pharmacotherapy of depression, especially in patients with severe cognitive impairment." (PMID 37894946, 2023). "Klotho treatment or Klotho overexpression have been shown to provide health benefits using animal models in certain other experimental settings, such as acute to chronic kidney injury progression, cognitive impairment, and sepsis." (PMID 38133288, 2023). "Augmenting platelet factors, possible messengers of klotho, may enhance cognition in the young brain and decrease cognitive deficits in the aging brain." (PMID 37587231, 2023). "However, studies with an aged amyloidogenic mice model have demonstrated that the overexpression of Klotho protein in the brain can improve AD-like pathology and cognitive impairment, and reverse neuronal damage." (PMID 35327507, 2022). "However, the neuroprotective effects of irisin compromised with the evidence of severe cognitive impairment, decreased protein expressions of MnSOD and FOXO3a, and increased ROS production in klotho knockout mice." (PMID 34306305, 2021). "Third, our present study demonstrated that irisin could improve cognitive impairment by upregulating klotho expression, but the exact mechanism of how irisin regulated klotho was undiscovered." (PMID 34306305, 2021). "Taken together, data confirmed that low-calorie and low-calorie high-protein diets could potentially reduce aging and cognitive deficits by elevation of Klotho (Graphical abstract)." (PMID 33072166, 2020). "The current findings showed that Klotho overexpression ameliorated cognitive deficits in AD mice." (PMID 32964663, 2020).
Cognitive impairment (continued). "In the view of the regulatory role of klotho in cognition and NMDAR function, we hypothesized that altered klotho was associated with the cognitive deficits in schizophrenia." (PMID 32612508, 2020). "This indicates that there is an interaction between Klotho and fibroblast growth factor-23, which jointly regulates the anti-oxidative stress of the body, improves the cognitive impairment of rats, and plays a role in protecting the kidney function, thus delaying aging." (PMID 32042011, 2020). "Based on accumulating evidence of anti‐AD effects of Klotho, we hypothesized that Klotho ameliorates Aβ pathology and cognitive impairment by promoting the transformation of microglia from M1 type to M2 type and regulating Aβ transporter function." (PMID 32964663, 2020). "But serum klotho was not an independent risk factor of cognitive impairment for hemodialysis patients with cerebrovascular disease (HR((95%CI) = 1.002(0.986–1.018), p = 0.776) or with cerebral infarction (HR(95%CI) = 1.005(0.987–1.023), p = 0.576)." (PMID 30791885, 2019). "The serum klotho level is a potential predictor of cerebrovascular disease in hemodialysis patients, but it is not an independent risk factor of cognitive impairment for hemodialysis patients with cerebrovascular disease." (PMID 30791885, 2019). "If this effect results from failure of FGF-23 signal transduction through Klotho, FGF-23-deficient mice may be expected show hippocampal-dependent cognitive impairment." (PMID 30911673, 2019). "Thus similar to what is observed with Klotho deficiency, FGF-23-deficient mice rapidly develop hippocampal-dependent cognitive impairment evidenced by impaired fear and spatial memory task performance." (PMID 30911673, 2019). "MCI is thought to be a form of pathological aging, and the study of the association between the Klotho gene and cognitive impairment and AD will no doubt bring new opportunities and hopes by adding a new direction in anti-aging research." (PMID 29088855, 2017). "Augmenting klotho or its effects may enhance cognition and counteract cognitive deficits at different life stages, promote the vitality of spermatogenesis, and ameliorate aging-related, Ang II-induced, or glomerulonephritis renal injury." (PMID 27885332, 2016). "In addition, there is a correlation of high TNF-α with a presence of low serum Klotho levels in HD patients with cognitive deficit as evaluated by Modified Mini Exam of Mental State (3MS) and Kidney Disease Quality of Life (KDQOL-sf) (unpublished data)." (PMID 25961830, 2015). "Lack of Klotho expression further leads to cognitive deficits." (PMID 23923038, 2013). "Preconditioning exercise alleviated neurological dysfunction and cognitive impairment in rats with cerebral ischemia, possibly associated with increased antioxidant capacity of neurons in the hippocampal CA1 region, due to the detection of increased Klotho and MnSOD expression." (PMID 38317957, 2024). "Klotho may antagonize oxidative stress, activate cellular autophagy, and inhibit neuroinflammation to reduce cognitive impairment by affecting the AMPK/SIRT1 signaling pathway, which plays an important role in glucose regulation, neuron proliferation, oxidative stress, and cognition.." (PMID 38505757, 2024). "The klotho protein may protect against cognitive impairment via multiple biological mechanisms." (PMID 36819720, 2023). "Our results probably presented a non-linear association of Klotho and cognitive impairment in CKD." (PMID 37560310, 2023). "In conclusion, the antioxidant and anti-inflammatory effects of Klotho mediated by Nrf2- NF-κB, as well as the modulation of glutamate neurotransmission function, seem to be novel signaling pathways involved in the pathogenesis of depression and cognitive impairments." (PMID 37894946, 2023).
Cognitive impairment (continued). "Although our findings do not implicate a causative mechanism of Klotho in AD, we provide evidence for a potential protective role of KL-VShet against Aβ-dependent tau pathology that is the key AD brain alteration linked to cognitive impairment." (PMID 34158479, 2021). "Therefore, increasing or activating the level of wild-type Klotho may increase the synaptic and cognitive functions, and may be beneficial in the treatment of AD or other types of cognitive impairments." (PMID 29088855, 2017). "The AAV-KL-shRNA-mediated decrease in KL levels in the hippocampus of female rats decreases the resilience of female rats to stress and diminishes sex differences in CUMS-induced cognitive deficit, anhedonic-like behaviors, and anxiety-like behaviors." (PMID 36674721, 2023). "This study clearly demonstrated that neuroprotective effect of Klotho by decreasing Tau-related symptoms, and the PET imaging showed less intensity of Tau symptoms compared to Aβ pathology and reduced the cognitive impairment." (PMID 35327507, 2022). "In another nephrectomized induced cognitive impairment rodent model, Klotho levels decreased in frontal cortex but not in hippocampus, accompanying with an increase in NF-κB and tumor necrosis factor-alpha levels." (PMID 37560310, 2023).